DOCK4 (dedicator of cytokinesis 4)
Description:
Functions as a guanine nucleotide exchange factor (GEF) that promotes the exchange of GDP to GTP, converting inactive GDP-bound small GTPases into their active GTP-bound form. Involved in regulation of adherens junction between cells. Plays a role in cell migration. [Isoform 2]: Has a higher guanine nucleotide exchange factor activity compared to other isoforms.
Synonyms: KIAA0716; FLJ34238
Tractability: Antibody: UniProt places it where antibodies can reach, with high confidence; its Gene Ontology location is reachable by antibodies, with high confidence. PROTAC: ubiquitination databases record sites on it; its protein half-life has been measured.
Gene: Protein-coding gene on chromosome 7 (111,726,110 to 112,206,407, reverse strand). Ensembl gene ENSG00000128512.
Subcellular location: Cell membrane; Cell projection; Cytoplasm, cytosol
Subcellular location (Human Protein Atlas): Nucleoli; Plasma membrane; Cytosol; Golgi apparatus
Pathways (Reactome):
Signal Transduction: RAC1 GTPase cycle; RAC2 GTPase cycle; RHOG GTPase cycle
Hemostasis: Factors involved in megakaryocyte development and platelet production
Gene Ontology:
Molecular function: guanyl-nucleotide exchange factor activity; PDZ domain binding; protein binding; receptor tyrosine kinase binding; small GTPase binding; GTPase activator activity
Biological process: cell chemotaxis; negative regulation of vascular associated smooth muscle contraction; positive regulation of vascular associated smooth muscle cell migration; regulation of postsynapse assembly; small GTPase-mediated signal transduction
Cellular component: cytosol; membrane; plasma membrane; cytoplasm; stereocilium; stereocilium bundle; glutamatergic synapse; postsynapse
Genetic constraint (gnomAD): Loss-of-function variants: 78 observed, 211.64 expected, observed/expected ratio (o/e) 0.37, 90% interval 0.31 to 0.44. The upper end of that interval is the gene's LOEUF score, 0.44, which puts it in group 1 of 6, group 1 being the genes least tolerant of losing a copy. Missense variants: 1,964 observed, 2,180.9 expected, observed/expected ratio (o/e) 0.9, 90% interval 0.87 to 0.94. Synonymous variants: 891 observed, 800.1 expected, observed/expected ratio (o/e) 1.11, 90% interval 1.05 to 1.18.
Homologues: Orthologues: macaque DOCK4 (99% identical), chimpanzee DOCK4 (99% identical), mouse Dock4 (98% identical), rat Dock4 (98% identical), guinea pig DOCK4 (98% identical), pig DOCK4 (98% identical), dog DOCK4 (97% identical), rabbit DOCK4 (95% identical), tropical clawed frog dock4 (88% identical), zebrafish dock4b (78% identical), zebrafish dock4 (73% identical), Caenorhabditis elegans ced-5 (22% identical), and 4 more. Paralogues in human: DOCK3 (57% identical), DOCK1 (35% identical), DOCK5 (34% identical), DOCK2 (33% identical), DOCK11 (16% identical), DOCK9 (15% identical), DOCK10 (15% identical), DOCK7 (15% identical), DOCK8 (15% identical), DOCK6 (14% identical).
Diseases named in the same sentence as DOCK4 in open-access papers:
DOCK4 is named in the same sentence as 71 diseases in open-access papers, as found by Europe PMC text mining. Sharing a sentence is not in itself a finding about the gene and the disease. The quoted sentences say what the papers report.
breast carcinoma (25 papers, 2018 to 2025). "A significant example is DOCK4 (Dedicator of Cytokinesis 4), identified as a biomarker for assessing the risk of bone metastasis in early-stage breast cancer." (PMID 40426987, 2025). "Overexpression of DOCK4 has been linked to tumor progression and poor survival rate in patients with breast cancer and liver cancer patients." (PMID 37037466, 2023). "In conclusion, high DOCK4 in early breast cancer is significantly associated with aggressive disease and with future bone metastasis and is a potentially useful biomarker for subsequent bone metastasis risk." (PMID 30426503, 2019). "However, DOCK4 has also been reported to promote breast cancer development and is associated with bone metastasis." (PMID 34783629, 2021). "DOCK4 expression has been previously linked to cell migration in vitro and to the risk of developing bone metastasis in breast cancer patients as well as correct axon guidance in vivo during embryo development, thus suggesting a prominent role of DOCK4 in regulating cell motility." (PMID 33202906, 2020). "Conversely, another study indicated that LncRNA AC073284.4 can inhibit epithelial-mesenchymal transition (EMT) and reduce migration in breast cancer cells by influencing the miR-18b-5p/DOCK4 axis." (PMID 40332167, 2025). "LncRNA AC073284.4 is able to inhibit epithelial-mesenchymal transition (EMT) and migration in breast cancer cells through the regulation of the miR‐18b‐5p/DOCK4 axis." (PMID 38443923, 2024). "We also show that brain endothelial cells promote paracrine stimulation of mesenchymal-like morphology of breast cancer cells via DOCK4, DOCK9, RAC1 and CDC42." (PMID 38762624, 2024). "In this study, we investigated the role of DOCK4 in the process of breast cancer cell extravasation and the growth of brain metastases." (PMID 38762624, 2024). "This activation is dependent on soluble factors secreted by brain endothelial cells, and occurs via the RAC1 GEF DOCK4, which is required for breast cancer cell extravasation to the brain in vivo." (PMID 38762624, 2024). "In this study we demonstrate how factors secreted by brain endothelial cells (BEC) activate EGFR signalling via DOCK4 to promote an elongated phenotype in breast cancer cells, thereby facilitating their successful extravasation to the brain." (PMID 38762624, 2024). "In breast cancer cells Dock4 localizes at the tips of membrane protrusions where it promotes cell migration via activation Rac139,40,62." (PMID 38802496, 2024). "As DOCK4 is a RAC1 GEF25, and RAC1 has been implicated in TEM26, we investigated the role of RAC1 in the adhesion and intercalation processes of breast cancer cells." (PMID 38762624, 2024). "DOCK4 activates Rac1 and promotes actin reorganization and formation of lamellipodia at the leading edge of breast cancer cells." (PMID 36059515, 2022). "In breast cancer cells, the lncRNA AC was used as a ceRNA to regulate miR-18b-5p and inhibit its negative regulatory effects on the expression of targeted DOCK4 genes." (PMID 35756659, 2022). "In our recent publication, we have described the discovery of the role of Dedicator of Cytokinesis 4 (DOCK4) as a potential biomarker protein predictive of bone metastasis within breast cancer." (PMID 31488945, 2019). "Our current study is supported further through analysis of DOCK4 gene expression within a publicly available database where high DOCK4 transcript levels predicted distant bone metastatic spread of breast cancer." (PMID 30426503, 2019). "Further studies of the mechanistic role of DOCK4 in breast cancer bone metastasis and implications for pharmacological inhibition are justified by our work." (PMID 30426503, 2019). "DOCK4 has been proven to be a potential marker for bone metastasis in early breast cancer." (PMID 38443923, 2024). "Hence, BEC promote metastatic extravasation through activation of EGFR signalling in breast cancer cells that requires DOCK4, DOCK9, RAC1 and CDC42, rendering them competent for extravasation." (PMID 38762624, 2024).
breast carcinoma (continued). "Previous research has identified DOCK4 as a potential biomarker for breast cancer bone metastasis." (PMID 38762624, 2024). "We investigated the cellular mechanism by which DOCK4 mediates breast cancer cell intercalation." (PMID 38762624, 2024). "Hence, we conclude that DOCK4 regulates the extravasation of breast cancer cells into the brain via controlling the stage of intercalation." (PMID 38762624, 2024). "However, the oncogenic activity of miR-18b-5p was shown in breast cancer cells where miR-18b-5p targets DOCK4, a significant cell division factor mainly involved in the regulation cell adhesion." (PMID 35190587, 2022). "DOCK4‐mediated activation of Rac1 has been demonstrated to promote actin reorganisation and the formation of lamellipodia at the leading edge of breast cancer cells 19, as well as the formation of lateral filopodia and blood vessel lumen morphogenesis within tumour angiogenesis." (PMID 30426503, 2019). "DOCK4 may therefore be a component of a protein panel that responds to elevated c‐MAF expression within bone‐homing breast cancer cells." (PMID 30426503, 2019). "Hence, common molecular mechanisms involving DOCK4/RAC1 may promote extravasation of breast cancer cells to the other metastatic sites." (PMID 38762624, 2024). "Next, we investigated whether DOCK4 is important for extravasation by injecting DOCK4 depleted cells into the internal carotid artery of mice and determining the percentage of breast cancer cells that localised inside or outside the brain blood vessels 5-days post intracarotid injection." (PMID 38762624, 2024). "Another study showed that DOCK4 expression level is downregulated in paclitaxel‐resistant breast cancers and lncRNA AC073284.4 might sponge miR‐18b‐5p to attenuate the invasion, metastasis, and epithelial–mesenchymal transition of breast cancer cells by upregulating DOCK4 expression." (PMID 34432380, 2021). "Proteomics identified Dedicator of Cytokinesis 4 as a biomarker predictive of bone spread, and this finding was further supported by the observation that high levels of Dedicator of Cytokinesis 4 within primary breast tumours were predictive of breast cancer spread to bone." (PMID 31488945, 2019). "Resolving the issue of how Spg integrates with the other signals that regulate MAPK activity could also be rather useful, given that DOCK3 and DOCK4 were previously shown to be required for the migration of melanoma and breast cancer cells, respectively, via activation of the Rho GTPase Rac." (PMID 30018198, 2018). "These experiments suggest that DOCK4 and RAC1 promote the intercalation of breast cancer cells into the brain endothelium via regulating cell elongation but not filopodial protrusions in response to endothelial-derived growth factors, such as EGF." (PMID 38762624, 2024). "Altogether, our data suggest that the brain endothelium and EGF contribute to extravasation by promoting DOCK4/RAC1- and DOCK9/CDC42-mediated elongation and intercalation of breast cancer cells." (PMID 38762624, 2024). "DOCK4 belongs to the DOCK180 family, which has diverse cell- specific functions and plays an important role in the metastasis of various tumors such as breast cancer, melanoma, and glioblastoma." (PMID 37324026, 2023). "Paclitaxel-resistant breast cancer tissue and cell line had downregulation of lncRNA which led to upregulation of miR-18b-5p and inhibited DOCK4 (Dedicator of cytokinesis protein 4)." (PMID 36685962, 2022). "Moreover, DOCK4 functions as a guanine nucleotide exchange factor for the GTPase Rac1, a key regulator of motility 14, 19, 20 and localises at actin‐rich protrusions in migrating breast cancer cells 19, while SNPs within the promoter region of DOCK4 have been detected in breast cancer." (PMID 30426503, 2019).
breast carcinoma (continued). "Breast cancer cells stimulated with conditioned media harvested from BEC (hCMEC/D3) showed an increased aspect ratio compared to cells stimulated with endothelial cell media (EC M) and this phenotype was blocked by DOCK4 depletion." (PMID 38762624, 2024). "Elongation assays showed that, like DOCK4-depleted cells, cells lacking either DOCK9 or CDC42 did not elongate upon EGF stimulation as control cells, suggesting that DOCK9 and CDC42, together with DOCK4 and RAC1, are essential for the elongation and subsequent intercalation of breast cancer cells." (PMID 38762624, 2024). "Knockdown of DOCK4 inhibits breast cancer cell entrance to the brain without affecting cancer cell survival or growth." (PMID 38762624, 2024). "BEC-conditioned media promote EGFR activation, breast cancer cell elongated morphology and filopodial protrusions; and knockdown of either DOCK4 or RAC1 reverses cancer cell elongation without affecting filopodia." (PMID 38762624, 2024). "Analysis revealed that DOCK4 does not play a role in the growth of breast cancer cells in the brain, as cells lacking DOCK4 are as efficient as control cells in tumour growth in the brain parenchyma." (PMID 38762624, 2024). "The miR-18b-5p/DOCK4 axis inhibits the EMT and migratory capacity of breast cancer cells." (PMID 33428596, 2021). "Constitutional genes with increased breast cancer relapse risk were claudin 15, WDFY2, golgin A4, DOCK4 while HCG27 and PLAC8L1 were among 18 signature signs not endorsed by prognostic index score." (PMID 33106505, 2020). "DOCK4 knockdown inhibited the migration of both PCC and BM cell lines, with inhibition being greater at 6 h than 12 h post‐assay initiation, suggesting that DOCK4‐mediated cell invasion may be important in the earlier stages of breast cancer cell migration." (PMID 30426503, 2019). "In vitro intercalation assays revealed that DOCK4 depleted breast cancer cells display a significant delay in intercalation compared to control cells; whereas adhesion assays performed in parallel showed that cancer cells lacking DOCK4 are as efficient as control cells in adhering to BEC." (PMID 38762624, 2024). "Additionally, breast cancer cells do not elongate in response to TGFβ stimulation, suggesting that EGF, but not TGFβ, stimulates the acquisition of an elongated phenotype via DOCK4." (PMID 38762624, 2024).
autism (17 papers, 2010 to 2025). Persistent deficits in social interaction and communication and interaction as well as a markedly restricted repertoire of activity and interest as well as repetitive patterns of behavior. "Animal experiments show that knock‐out of Dock4, a gene that is closely associated to autism, leads to loss of hippocampal‐based spatial memory significantly earlier than in the control group." (PMID 39192595, 2024). "In parallel, Dock4 has been linked to the risk of autism, where Dock4-knockout mice reportedly exhibit autism-related behaviors." (PMID 37783686, 2023). "The DOCK4 rs2217262 allele is linked with autism in both the Caucasian and Han populations in northern China." (PMID 36882763, 2023). "DOCK4 is located at chromosome band 7q31.1, an autism-susceptible locus resided by several ASD-associated genes involved in development and language regulation." (PMID 31388105, 2021). "A comprehensive single nucleotide polymorphism (SNP) genotyping, association and copy number variation study in Caucasian autism families identified the linkage between DOCK4 and ASD." (PMID 32244264, 2020). "Our previous study using Dock4 knockout mice have revealed that Dock4 deficiency in vivo leads to autism-like behaviors, including defects in social novelty preference and communication." (PMID 32009906, 2019). "Single nucleotide polymorphisms within DOCK4 were associated with autism risk in different populations." (PMID 23083465, 2012). "Moreover, studies have demonstrated that the rs2074130 and rs2217262 polymorphisms of DOCK4 are associated with the risk of autism and schizophrenia, respectively." (PMID 36882763, 2023). "Hence, the two autism/dyslexia-linked mutants of Dock4 showed impaired abilities on activation of both Rac1 and Rap1." (PMID 32009906, 2019). "Association studies investigating WNT2, DISC1, MET, DOCK4 or AHI1 also provide evidence that the canonical Wnt pathway might be affected in autism." (PMID 23083465, 2012). "Dock4 deficiency causes a marked reduction in hippocampal Rac1 activity, while hippocampal Rac1 replenishment in the Dock4 KO mice reverses autism-like social impairments in these mice." (PMID 37445914, 2023). "Dysfunctional DOCK4 is also involved in several neuropsychiatric disorders, including autism, dyslexia, mild intellectual disability, schizophrenia and hearing impairment." (PMID 33968925, 2021). "Another family-based association study focused on zinc finger protein 533 (ZNF533), DOCK4, and IMMP2L genes in the Chinese Han population showed that SNPs within ZNF533 and DOCK4 were related to autism, whereas IMMP2L was shown irrelevant." (PMID 32244359, 2020). "Several subsequent studies using SNP analysis reported multiple SNPs and chromosome microdeletions or duplications of DOCK4 in autism and/or dyslexia patients." (PMID 32244264, 2020). "Two DOCK4 variations have been identified in individuals with dyslexia and/or in autism subjects with poor reading abilities." (PMID 32009906, 2019). "The first variation, identified in individuals from a European family with autism and/or reading/spelling difficulties, is a microdeletion at the junction of DOCK4 and its neighboring gene IMMP2L (deletion at chr7:110663978-111257682, GRCh37)." (PMID 32009906, 2019). "This study provides insights in understanding the common molecular pathophysiology of autism and dyslexia by investigating their shared gene DOCK4." (PMID 32009906, 2019). "DOCK4 in the AUTS1 locus on chromosome 7q31.1 was proposed as a dyslexia candidate gene in a study of autism." (PMID 23308072, 2012). "Further evidence for a role of DOCK4 in autism was provided by the finding of a microdeletion CNV in an autistic sib-pair and a deletion in a family with dyslexia." (PMID 23083465, 2012). "The data thus suggest that diminished DOCK4 level (and presumably, function), as found in autism, suppresses Wnt signaling and dendrite growth." (PMID 23083465, 2012).
autism (continued). "We assessed the frequency of DOCK4 CNVs in 197 additional multiplex IMGSAC autism families (320 affected individuals) and 461 Caucasian control subjects using six exonic QMPSF probes." (PMID 20346443, 2010). "Recent studies have revealed the important role of Dock4 in autism-like social deficit." (PMID 39282658, 2024). "Similarly, other autism candidate genes including NLGNs, IQSEC2, DOCK4, and STXBP5, are also implicated in AMPAR trafficking." (PMID 38316900, 2024). "To study whether the autism/dyslexia-linked variations of DOCK4 have influences on its Rac1 GEF activity, we compared the abilities of Rac1 activation by Dock4-945VS and R853H with that of the wild-type (WT) protein when exogenously expressed in cells." (PMID 32009906, 2019). "In one Dutch family, autistic siblings carried a maternally inherited microdeletion that created a fusion of DOCK4 and another gene, IMMP2L, and a paternally-inherited microdeletion that disrupted a gene in the contact in associated protein family (CNTNAP5) that has been implicated in autism." (PMID 23308072, 2012). "A recent AUTS1 fine-mapping study, using both family-based and case-control association analyses, detected SNPs within DOCK4 (dedicator of cytokinesis 4) and IMMP2L (IMP2 inner mitochondrial membrane protease-like) that may be indexing autism susceptibility factors." (PMID 20346443, 2010). "Further studies to elucidate the role of DOCK4 in human neuronal cell lines and more generally the role of GEF regulators of small GTPases in autism and dyslexia are now warranted." (PMID 20346443, 2010).